IL33 (interleukin 33)
Diseases named in the same sentence as IL33 in open-access papers (continued):
Sharing a sentence is not in itself a finding about the gene and the disease.
infection (continued). "To determine if IL-33 was released during brain T. gondii infection, we first utilized an ex-vivo assay to measure extracellular IL-33 during infection." (PMID 33108405, 2020). "Our results are slightly at odds with a previous publication that demonstrated that KLRG1+PD‐1+ ILC2 produce more Th2 cytokines following both IN delivery of IL‐33 and during infection with the worm Nippostrongylus brasiliensis." (PMID 31742928, 2020). "Parasite burdens in the intestine day 6 p.i. were reduced when IL-33 was applied before infection and also i.p. application of IL-33 after completion of the tissue migration phase at day 4 and 5 p.i., reduced the intestinal parasite burdens on the next day." (PMID 33351862, 2020). "This pleiotropic nature of IL‐33 and unique ST2 expression likely explains why IL‐33 participates in infection, inflammation, tissue homeostasis and repair within these immune cellular networks." (PMID 32566227, 2020). "In the gastric mucosa of patients infected with H. pylori, during the acute phase of infection, enhanced expression of IL-33 suggests the role of this cytokine in activating immune cells and controlling gastric tissue homeostasis." (PMID 32151084, 2020). "Previous studies have proven the functions of IL-33 against infection with various parasites, including Schistosoma japonica, Angiostrongylus, Trichuris muris, and hookworm." (PMID 32156309, 2020). "IL-33 and demonstrating the importance of the endogenous IL-33 response during the early stages of infection." (PMID 33351862, 2020). "In the specific case of MTB, IL-33 has been shown to have protective effects in infected animals, as well as a therapeutic effect when given systemically post-infection." (PMID 32508826, 2020). "Another study demonstrated that infection in mice, with the fungal pathogen P. murina, induced pulmonary system-specific production of IL-33 and M2 alveolar macrophages that were capable of mounting immune responses against P. murina." (PMID 32486265, 2020). "Development of AHR was abrogated and numbers of CD4+ Th2 cells were reduced in re-infected neonates that had been pretreated with an anti-IL-33 antibody during primary infection compared to mice that received a control antibody." (PMID 32397226, 2020). "Previous studies in Balb/c mice showed that the alarmin IL-33 derived from alveolar type 2 epithelial cells is an important trigger of lung type 2 cytokine production both at early and late phases of infection with a highly virulent C. neoformans strain." (PMID 32117319, 2020). "This is consistent with the fact that ILC2s and Th2 cells are involved in resistance to infection in an IL‐33‐dependent manner." (PMID 32566227, 2020). "Interleukin-33 (IL-33) is an epithelial-derived cytokine that can be released upon tissue damage, stress, or infection, acting as an alarmin for the immune system." (PMID 33329534, 2020). "Innate cytokines, including TSLP, IL-25 and IL-33, which are secreted following infection of murine and human airway epithelial cells by RSV, are known inducers of ILC2 differentiation and activation." (PMID 32375305, 2020). "IL-33 plays critical roles in metabolic homeostasis, infection, inflammation, cancer and central nervous system diseases." (PMID 32390869, 2020). "Consistent with its role as a pre-stored alarmin, IL-33 is highly expressed in the brain at baseline, and only mildly increases with infection." (PMID 33108405, 2020). "Interleukin 33 (IL-33) belongs to IL-1 family of cytokines, and participates in various biological activities, including inflammation, immune response and the infection process." (PMID 33324412, 2020). "The pleiomorphic cytokine interleukin-33 (IL-33) exerts various roles during infection, either protective or detrimental." (PMID 32571430, 2020). "Alternatively, alveolar macrophages are also a source of IL‐33 in H3N1 Mem/71 influenza virus‐infected mice where ILC2 activation peaks at day 6–9 post infection." (PMID 29762870, 2019).
infection (continued). "Western blot showed a gradual increase in the expression levels of processed IL-33 and ST-2 following H. pylori infection in the first 9 h; however, upon infection for 12 to 24 h, the expression levels decreased." (PMID 31640262, 2019). "IL-33 production during an infection can modulate Th1- and Th17-exacerbated inflammation, contributing to lesser tissue damage." (PMID 31320834, 2019). "IL-33 drives colonic group 2 innate lymphoid cell (ILC2) activation during infection and IL-33 activated ILC2s are sufficient to prevent disease." (PMID 31221971, 2019). "IL-33 is a more recently identified IL-1 family member with important functions in regulating infection, inflammation and cancer." (PMID 31383884, 2019). "Accordingly, mast cells and ILC2s respond through the IL-33/ST2 axis to the damaged intestinal mucosa arising from acute injury or infection." (PMID 31227713, 2019). "IL-33, a member of the IL-1 cytokine family, is released as a danger signal or “alarmin” in response to infection or cellular stress and exhibits a wide range of functions that aid immune clearance of microbes and parasites." (PMID 30635396, 2019). "An infection with a large amount (about 106 plaque forming unit (PFU) per mouse) of influenza virus has been shown to induce IL-33 secretion." (PMID 31509992, 2019). "Such IL-33 production, particularly in the early phases of infection, can act in synergy with IL-18 and IL-1α/β in the recruitment of NK, iNKT, and T cytotoxic cells." (PMID 31507607, 2019). "IL-33 was administered in five doses by intraperitoneal injection (0.75 μg/mouse) prior to infection." (PMID 31221971, 2019). "This is likely caused by gut leakiness still present in IL-33-treated mice, as demonstrated by FITC-dextran still present within their serum during infection." (PMID 31221971, 2019). "Unlike the IL-33 treatment model, ST2−/− knockout mice had no change in colon neutrophilia during CDI, indicating endogenous IL-33 dominantly regulates colonic eosinophil recruitment during infection." (PMID 31221971, 2019). "Some research has shown that IL-33 plays a crucial role in immune-mediated disorders, for instance, infection, inflammation, and autoimmune diseases." (PMID 31889095, 2019). "These experiments provide further evidence that IL-33 influences the function of T cells in disease and this effect is highly dependent on the target tissue of infection and type of pathogen." (PMID 30949175, 2019). "During primary infection, IL-33 enhances the response of naive CD8+ T cells and is necessary for virus control." (PMID 31447845, 2019). "At seven days post-infection, we isolated cells from lungs injected with exogenous IL-33 daily for five days prior to infection." (PMID 31509992, 2019). "Both qPCR and ELISA analyses indicated upregulation of IL-33 in response to both hypervirulent R20291 and attenuated R20291_cdtb infection." (PMID 31221971, 2019). "As with other immunomodulating therapies, investigations on the effect of attenuating IL-33/ST2 axis on immune defense against infection and other immune responses are essential before further therapeutic development." (PMID 30886621, 2019). "This work advances our fundamental understanding of the host immune response to C. difficile, demonstrating an important role for IL-33 responsive ILC2s in recovery and barrier protection during infection." (PMID 31221971, 2019). "ILC2s isolated from IL-33-treated mice had 2.5-fold increase in IL-13+ ILC2s during infection compared with controls." (PMID 31221971, 2019). "In summary, memory CTLs emerging from an IL-33-deprived environment were fully functional and protective, and displayed a largely normal phenotype upon secondary infection." (PMID 31447845, 2019). "IL-33-treated mice had significantly more goblet cells per colonic crypt during CDI infection compared with untreated controls." (PMID 31221971, 2019).
infection (continued). "Overall, exogenous IL-33 enhanced the secretion of IL-12p40 in BAL fluids post-infection, amplified IL-12 production, and increased the maturation of BMDCs." (PMID 31509992, 2019). "To assess the relevance of IL-33 during C. difficile infection, we quantified IL-33 protein and RNA during R20291 and R20291_cdtb infections and in uninfected controls." (PMID 31221971, 2019). "IL-33−/− mice demonstrated significantly less weight loss during lethal infection with O. tsutsugamushi, and exogenous recombinant IL-33 treatment had exacerbated disease following sublethal infection." (PMID 31555249, 2019). "We therefore used intravascular staining to determine if Il33−/− mice truly lack the ability to generate CD8+ TRM cells after infection with MCMV." (PMID 30635396, 2019). "Schistosoma mansoni-infected participants displayed lower levels of plasma IL-33 suggesting the possible depletion of plasma IL-33 during infection." (PMID 31849991, 2019). "In detail, this infection over-expressed IL-33, involving the MyD88 pathway by activating TLR4 signaling." (PMID 31130612, 2019). "Our recent finding that that IL-33 increases neutrophil recruitment and thereby increases bacterial clearance during super-infection implicates mature neutrophil function in bacterial clearance in this context." (PMID 31159430, 2019). "miRNA differentially expressed between naïve ILC2 and ILC2 following in vivo IL33-stimulation or N. brasiliensis-infection, and T cells upon N. brasiliensis-infection indicated considerable co-incidence of miRNA modulation." (PMID 30356668, 2018). "Real-time PCR and Western blot analyses were performed 96 h after infection to evaluate the level of IL-33 mRNA and protein expression." (PMID 29329586, 2018). "It has been demonstrated that intestinal baseline IL-33 expression was present in pericryptal fibroblasts and was increased during infection." (PMID 30405626, 2018). "IL-33, a recently discovered member of IL-1 family, exercising its role as an alarm signal (alarmin) in response to cellular damage induced by infection or injury to alert immune cells expressing the ST2 receptor (IL-1RL1)." (PMID 30564243, 2018). "IL-33 AAV treated C57BL/6 mice produced significant increased BAFF levels as early as 1 week after infection compared with LacZ AAV treated mice." (PMID 30574145, 2018). "LEPCs release innate cytokines, such as TSLP, IL-33, and IL-25, in response to infection or various environmental factors." (PMID 30056803, 2018). "IL-33 is a direct target of miR-203-3p in HSCs, and downregulation of miR-203-3p leads to elevated levels of IL-33 in HSCs, initiating type 2 pathology after infection." (PMID 29554131, 2018). "After infection with influenza virus, IL-33/ST2 signaling was involved in ILC2-dependent restoration of airway epithelial integrity." (PMID 29977243, 2018). "Depending on the context of certain infections, IL-33 was either protective or even deleterious because it can either play a beneficial role in the resolution of inflammatory processes, or it can contribute to aggravating inflammation, respectively." (PMID 29728738, 2018). "IL-33 is initially recognized as potent stimulator of adaptive immune response polarization toward T helper (Th) 2 phenotype following infection or exposure to allergens." (PMID 30001716, 2018). "For example, during infection, neutrophil proteases played important roles for IL-33 activation, but mast cell proteases predominated during allergic type-2 inflammation." (PMID 29691371, 2018). "To determine the expression of miRNAs in ILC2 following activation, we isolated ILC2 (CD3−CD4−Lineage−ICOS+) from the abdominal lymph nodes of naïve wildtype (WT) mice or WT mice treated with IL-33 or infected with N. brasiliensis (day 5 post-infection)." (PMID 30356668, 2018). "It is noteworthy that IL-33 expresison in HSCs begins to elevate at day 42 after infection, thus, this mechanism mainly exerts its role in the progression of Th2 pathology after 42 days." (PMID 29554131, 2018).
infection (continued). "Our data showed that, similar to the expression pattern in whole liver, the expression of miR-203-3p in hepatocytes and HSCs began to decrease at day 42 post-infection, while the level of Il33 mRNA was elevated at the same time." (PMID 29554131, 2018). "In response to tissue damage, infections or necrosis IL-33 is released in the extracellular space, where it functions as an alarmin for the immune system." (PMID 30483263, 2018). "Our initial findings were also validated in vMC0-infected BN rats, where infection resulted in the induction of genes associated with macrophage M2 activation (MGL1, ARG1, IL10, and IL10RA) and Th2 genes (IL33 and IL25)." (PMID 30150981, 2018). "In the present study, we showed that combination treatment of H2O2 and a synthetic viral dsRNA analogue and a TLR3 ligand, poly (I:C) or rhinovirus-infection significantly increased the expression of IL-33 compared with each treatment alone." (PMID 29587772, 2018). "Our data showed that the initial elevation of IL-13 in hepatic ILC2 cells (day 32 post-infection) occurs prior to the elevation of IL-33 in whole livers and HSCs (day 42 post-infection)." (PMID 29554131, 2018). "This is interesting because previous research suggest that IL-33 is one of the so called alarmins which initiate tissue recovery after damage or infection." (PMID 28423364, 2017). "Our current data now show that Th2 cell-expressed AREG in an autocrine fashion facilitates the IL-33-induced expression of IL-13 at the site of infection." (PMID 29045902, 2017). "Constitutive expression of IL-33 in epithelial cells suggests that IL-33 is used as an alarmin in response to infection or injury." (PMID 28484466, 2017). "Rodent immune cells, such as macrophages and dendritic cells have been shown to produce IL-33 during allergic inflammation and infection." (PMID 28168040, 2017). "The number of IL-33-expressing hepatocytes was significantly increased following L2-MHV3 infection with a higher number at 72 h PI." (PMID 28607531, 2017). "IL-33 thus serves as a nuclear alarmin to sense damage and alert adjacent cells and tissues following infection or tissue injury, and therefore has the potential to influence a broad range of diseases." (PMID 28387719, 2017). "IL-33 mRNA expression peaked at day 4 post infection in the liver and correlated well with the kinetics of viral replication in this organ and subsequent hepatic inflammation, confirming its role as an alarmin." (PMID 28448566, 2017). "In order to dissect the in vivo impact of MCMV infection on IL-33 expression, we have measured IL-33 mRNA levels at day 1.5, 4, 7 and 10 post infection in the liver of BALB/c mice." (PMID 28448566, 2017). "In patients that follow a complicated course (which includes pulmonary dysfunction and an increase in infection rates), the IL33 elevations are greater and persist over several days when compared to similarly injured patients with uncomplicated courses." (PMID 28742815, 2017). "IL-33 levels are increased in the plasma of infants with severe malaria, as compared with infection-free controls." (PMID 28448579, 2017). "The CXCL10 and CXCL11 were significantly induced during L2-MHV3 infection in both WT and IL-33 KO mice with an exacerbated manner especially at 72 h PI in IL-33 KO context." (PMID 28607531, 2017). "IL-33 is an IL-1 family cytokine that is expressed in barrier tissues, possesses a protective role during infections and promotes a Th2 immune response." (PMID 28423364, 2017). "We found that WT mice upregulated Il33 expression in response to H. pylori infection up to 350%, while upregulation in the Dmbt1−/− reached 52% in response to the infection." (PMID 28423364, 2017). "The mRNA expression of TNFα revealed a strong induction during L2-MHV3 infection in WT and IL-33 KO mice, although enhanced expression was found in IL-33 KO mice especially at 48 h PI." (PMID 28607531, 2017).
infection (continued). "In MCMV infected livers, IL-33 was found to be concentrated in a large number of cells that form focal infiltrates by selectively surrounding the foci of infection." (PMID 28448566, 2017). "PbA-infection triggered a dramatic increase of IL-33 expression by oligodendrocytes, through ST2 pathway." (PMID 28448579, 2017). "Full length IL-33 is released into the extracellular matrix during tissue damage, cell necrosis, or mechanical stress, following exposure to allergens or infection with viruses or parasites." (PMID 28387719, 2017). "As the IL-33 KO mice were more sensitive to L2-MHV3 infection, we measured the viral amplification in the liver by quantification of viral nucleocapsid coding RNA." (PMID 28607531, 2017). "IL-33 was thus proposed to act as an alarmin to sense damage and alert neighboring cells and tissues following infection or trauma and therefore has the potential to influence a broad range of diseases." (PMID 28168040, 2017). "This likely occurred in C57BL/6 but not in Cftr−/−mice in which the high levels of epithelial damage observed upon the infection likely accounted for the sustained IL-33-dependent ST2+ILC2 expansion." (PMID 28090087, 2017). "The expression of IFNγ increased after the L2-MHV3 infection in WT mice, whereas less profound induction was observed in IL-33 KO mice." (PMID 28607531, 2017). "To delineate the role of IL-33 in the regulation of infiltrated cells during L2-MHV3 infection, we investigated the effect of IL-33 ablation on resident immune cells infiltration in the liver following L2-MHV3 infection by flow cytometry." (PMID 28607531, 2017). "IL-33 treatment enhanced the neutrophil influx to the site of infection and thus led to more efficient bacterial clearance and reduced mortality in CLP-induced septic mice." (PMID 28168040, 2017). "The IL-33 KO mice were more sensitive to L2-MHV3 infection exhibiting higher levels of AST/ALT, higher tissue damage, significant weight loss, and earlier death." (PMID 28607531, 2017). "A global decrease in liver infiltrate cell number was observed, especially for the immune cell populations of B lymphocytes, T lymphocytes, NKT cells, and macrophages in the WT mice but more importantly in the IL-33 KO mice following L2-MHV3 infection." (PMID 28607531, 2017). "While microglia activation was not affected by ST2 deficiency, the inhibition of neurogenesis and the production of inflammatory mediators in the hippocampus after PbA-infection depended upon IL-33/ST2 pathway." (PMID 28448579, 2017). "We then compared the expression level of IL-33 in serum from mixed sex infection and male-only infection mice at 4, 7, and 10 weeks post-infection." (PMID 27445267, 2016). "On viral and parasitic experimental infections, IL-33 plays a crucial role in the local immune response to several different pathogens." (PMID 27334012, 2016). "The expression of IL-33 mRNA in Ca9-22 cells significantly increased from 24 to 48 h after infection with P. gingivalis W83 and after stimulation with lyophilized whole cells of P. gingivalis." (PMID 27058037, 2016). "As IL-33 increased as early as 2 dpi in the livers and remained at similar levels throughout the course of infection, ST2L expression in the liver was also significantly increased at 6 and 10 dpi." (PMID 26943125, 2016). "Overall, this study indicates a significant role of IL-33 alarmin in endothelial activation and renal damage, highlighting infection-triggered EC damage and IL-33-mediated pathological changes during the course of O. tsutsugamushi infection." (PMID 26943125, 2016). "The authors conclude that in COPD, smoke alters the lung microenvironment to facilitate an alternative IL-33-dependent exaggerated proinflammatory response to infection, exacerbating disease." (PMID 27001429, 2016). "Our data demonstrate that infection with O. tsutsugamushi Karp strain can increase gene expression of IL-33 and ST2L in the kidneys and liver." (PMID 26943125, 2016).